RNU6-602P (RNA, U6 small nuclear 602, pseudogene)
Gene: Small nuclear RNA gene on chromosome 14 (31,662,039 to 31,662,143, reverse strand). Ensembl gene ENSG00000223087.
Homologues: Orthologues: chimpanzee U6 (95% identical), macaque U6 (90% identical). Paralogues in human: RNU6-188P (79% identical), RNU6-684P (79% identical), RNU6-1024P (78% identical), RNU6-310P (78% identical), RNU6-1316P (77% identical), RNU6-15P (77% identical), RNU6-532P (77% identical), RNU6-80P (77% identical), RNU6-1145P (76% identical), RNU6-1175P (76% identical), RNU6-1260P (76% identical), RNU6-1289P (76% identical), and 1288 more.